MMP2 (matrix metallopeptidase 2)
Diseases named in the same sentence as MMP2 in open-access papers (continued):
Sharing a sentence is not in itself a finding about the gene and the disease.
glaucoma (continued). "In summary, our study showed that the expression levels of TNF-α, IL-2, IL-6, IL-8, BDNF, MMP-2, MCP-1, VEGF, IFN-γ, LT-α, bFGF, PDGF-AA, and TIMP-1 were different among the 3 types of glaucoma." (PMID 36254076, 2022). "However, the level of MMP-2 in aqueous humor in patients with glaucoma remains unclear." (PMID 35457074, 2022). "The TIMP-2 levels were significantly elevated in both glaucoma (POAG and PEXG) and PES subjects, while MMP-2 was higher in PEXG and PES subjects, when compared to samples from controls." (PMID 34439995, 2021). "Strikingly, these MMP-2 null mice showed reduced levels of TNF, a proinflammatory cytokine with a well-documented neurodegeneration-exacerbating function in glaucoma." (PMID 26451076, 2015). "The up-regulation of several MMPs specifically MMP-2, MMP-9, and MMP-13 are reported in steroid induced mice model of glaucoma." (PMID 25988186, 2015). "Clinical Relevance of MMPs as Biomarkers: Elevated levels of specific matrix metalloproteinases (MMPs), particularly MMP-2 and MMP-9, may serve as potential biomarkers for the progression of glaucoma." (PMID 40698094, 2025). "Our results confirm elevated MMP-2 and MMP-3 levels in glaucoma AqH." (PMID 41154592, 2025). "Increased levels of MMP-2, CTGF, and TIMP-2 were observed in 60 glaucoma patients (30 PEXG and 30 POAG) when compared to controls, which may involve changes during the pathogenesis of the disease." (PMID 34439995, 2021). "The increase in TIMP1 and TIMP2 may lead to the inhibition of MMP2 activity and contribute to the IOP of primary open-angle glaucoma." (PMID 33195434, 2020). "MMP2 may play an important role in the balance between ECM synthesis and degradation and could potentially be a novel target for glaucoma intervention." (PMID 32719611, 2020). "Previous studies have shown that MMP-2 and MMP-9 may play major roles in the pathogenesis of steroid induced glaucoma as their levels were decreased in human TM cells treated with steroid." (PMID 23977299, 2013). "Metalloproteinases (MMP-2 and MMP-9) are upregulated in the optic nerve head of glaucoma patients." (PMID 18334938, 2008). "Interestingly, these findings may indicate that MMP-2 expression is not independent, and imbalances in the MMP-2/TIMP-2 ratio may be significant in the pathogenesis of ocular hypertension in glaucoma." (PMID 35457074, 2022). "MMP2, MMP3, and TIMP1 were also detected in higher, but not significantly different, amounts in aqueous samples of primary open-angle glaucoma eyes." (PMID 41009516, 2025). "They found that MMP2, MMP3, TIMP1, and TIMP2 were detected at significantly higher concentrations in aqueous samples from eyes with pseudoexfoliation with and without glaucoma compared with cataractous eyes." (PMID 41009516, 2025). "We also found an increased expression of MMP-2, MMP-3, MMP-9, TGFβ-1, and TGFβ-3 in eyes with JIAU, independent of the presence of glaucoma." (PMID 29675026, 2018). "In another study, mRNA expression of MMP-1 (but not MMP-2, MMP-9, and MMP-13) was found to be significantly up-regulated in steroid induced sheep model of glaucoma." (PMID 25988186, 2015).
metastatic tumors (33 papers, 2002 to 2025). "MMP-2 expression is associated with higher incidence of metastatic diseases and lower survival rate." (PMID 26942004, 2016). "The expression of MMP-2 immunoreactive protein has been associated with invasive and metastatic tumours in previous in vitro studies." (PMID 14520459, 2003). "Elevated expression of MMP-2 is closely associated with tumor invasion, angiogenesis, metastasis, and recurrence, suggesting its significance as a therapeutic target in combating aggressive and metastatic tumor phenotypes." (PMID 39431222, 2024). "Some miRNAs, including miR-340, can induce the migration of these cells in human BC cell lines by regulating the expression of MMP-2 and MMP-9; however, silencing of miR-340 expression is associated with high-grade and metastatic tumors." (PMID 41356146, 2025). "We found that the expression of TWIST1, SNAI1, ZEB1, hFN1, and MMP2 increased from healthy epithelial cells to primary and metastatic tumor cells, reaching the highest expression in mesenchymal cell models." (PMID 40332096, 2025). "What is more, in metastatic tumors (N1 + N2) primary cancer was characterized by a significantly higher content of MMP2 (+0.660-fold), 3-nitrotyrosine (+0.594-fold), and lower Nrf2 (−0.600-fold) and lkB (−0.954-fold) expressions." (PMID 38397798, 2024). "In particular, MMP2 (gelatinase-A) and MMP9 (gelatinase-B) are deeply associated with the presence of metastatic tumors." (PMID 36612089, 2022). "It has been confirmed that the expression levels of MMP-9 and MMP-2 in GC, especially in metastatic tumors, are noticeably higher than those in normal gastric mucosa." (PMID 34540679, 2021). "MMP-9 and MMP-2, which are highly expressed in metastatic tumors, are the only two type IV collagenases that are necessary prerequisites for cell invasion." (PMID 28878295, 2017). "Increased MMP-2 in primary prostate tumors predicts the future development of metastatic disease in human studies." (PMID 24798191, 2014). "In men with metastatic disease MMP-2 expression was present in all CPCs and DTCs as well as mM but was expressed in all parts of the bone marrow fragment, defined as central expression." (PMID 23227342, 2012). "The finding that active MMP-2 in normal mucosa is also inversely correlated with stage of disease and with distant metastatic disease is remarkable." (PMID 12085179, 2002). "The secretion of MMP-2 and MMP-9 by cancer cells is an important mechanism of the cell invasion process since these enzymes degrade basal membrane components such as type IV collagen, a process associated with highly invasive and metastatic tumors." (PMID 38137922, 2023). "They discovered that miR-1233-3p was a target of circEHMT1 and showed that circEHMT1 could regulate MMP2 (matrix metallopeptidase 2), which is upregulated at sites of tissue damage, inflammation, and in stromal cells surrounding the invading front of metastatic tumors." (PMID 33717646, 2021). "In CAFs from metastatic tumors, a decrease in CCL2, MMP-2, TNC, OPN, and TGFβ levels and an increase in only TIMP1, PDPN, and SPP1 mRNA levels (without an effect on protein levels) was observed after calcitriol treatment." (PMID 38360633, 2024). "Another study indicated that inhibition of MMP-2/MMP-9 improves the efficacy of PD-1 or CTLA4 blockade in the treatment of primary and metastatic tumors." (PMID 35178444, 2022). "Among all MMPs that are highly expressed in the tumor-bone microenvironment (MMP-2, -3, -7, -9, and -13), only osteoclast-derived MMP-7 significantly contributed to human breast-to-bone metastatic tumor growth and tumor-induced osteolysis in experimental mice." (PMID 24978435, 2014). "The expression of p-STAT3, STAT3, MMP-2, and MMP-9 in metastatic tumors by western blot analysis." (PMID 34526411, 2021).
metastatic tumors (continued). "In vivo studies indicated that compared with using DS or HIF-1α knockdown alone, DS with HIF-1α knockdown can better suppress the volume and number of metastatic tumors, and reduce the mRNA and protein expressions of HIF-1α, MMP-2, TGF-β, Twist and N-cad in metastatic tumor tissues of nude mice." (PMID 33976746, 2021). "MMP-2 was expressed in 85 % of the non-metastatic tumours and in all the metastatic tumours, while E-cadherin was expressed in 85 % of the non-metastatic tumours and in 66 % of the metastatic tumours." (PMID 27486511, 2015). "To investigate whether MMP-2 and MMP-7 were up-regulated by ATF4 in vivo, we performed immunohistochemistry in the metastatic tumors that had been injected with the TE-1LM-ATF4, TE-1HM-SCR, and TE-1HM-siATF4 cells." (PMID 25078779, 2014). "In low grade tumors, mM and surrounding stromal cells were MMP-2 negative, with variable expression in high grade tumors; in metastatic disease, both mM and stromal cells were MMP-2 positive." (PMID 23227342, 2012).
thyroid cancer (33 papers, 2010 to 2024). "Parallel to the decreased invasive capacity in association with treatment with galectin-3 inhibitors, MMP2 expression progressively diminished when thyroid cancer cells were treated with increasing doses of GB1107 or TD139." (PMID 34035807, 2021). "In concordance with ZEB1 upregulation, expression of mesenchymal markers N-cadherin and MMP2 was increased in thyroid cancer cells subjected to heat treatment at 40°C." (PMID 38394093, 2024). "Streptavidin-ZAP conjugated to biotinylated Chlorotoxin (CTX-SAP) was used to selectively target Matrix Metallopeptidase 2 (MMP-2), which is known to be expressed by ML-1 thyroid cancer cells." (PMID 36977072, 2023). "In vitro experiments of co-cultures revealed that the interaction between fibroblasts and thyroid cancer cells increases the secretion of pro-MMP-2 and pro-MMP-9 in the supernatants." (PMID 36077709, 2022). "On the other hand, the AEG-1 targets MMP2/9 in thyroid cancer cells and enhances cell invasion and migration by inducing the MMP2/9." (PMID 36232606, 2022). "The authors have shown that the siRNA-mediated silencing of this gene led to a significant down-regulation of the EMT markers Slug, Twist1, and matrix metalloproteinase 2 (MMP-2) in thyroid carcinoma cells." (PMID 32230926, 2020). "We next investigated the importance of MMP2 and –9 per se on the invasion of the cells, as these two MMPs are important for thyroid cancer cell invasion." (PMID 29734379, 2018). "In thyroid cancer ML-1 cells, S1P was able to enhance calpain activity and MMP2 and -9 secretion, thus enhancing invasion." (PMID 29734379, 2018). "Collectively, our data suggest that the role of Trop2 on thyroid cancer cell invasion and migration was mediated by regulation of MMP2." (PMID 28709407, 2017). "In summary, we show that Trop2 is overexpressed in thyroid cancer and promotes the invasion and migration of thyroid cancer cells via MAPK ERK/JNK/AP1/MMP2 signaling, potentially offering new molecular targets for treatment of thyroid cancer." (PMID 28709407, 2017). "Many MMP family members, such as MMP2, MMP7, MMP9, MMP11, and MMP13, have been implicated to be associated with the development and progression of thyroid cancer." (PMID 28709407, 2017). "Given a strong link between matrix metalloproteinases (MMPs) and tumor metastasis, we also tested the effect of altered expression of N-cadherin on the expression of MMP-2, -9 and -14 in thyroid cancer cells." (PMID 28042956, 2017). "To further confirm the role of Trop2 in thyroid cancer, we evaluated the effects of over-expressing Trop2 on the MMP2 expression in FTC-133 cells." (PMID 28709407, 2017). "The results from clinical specimens showed that Trop2 expression correlated with MMP2 expression in primary thyroid cancer." (PMID 28709407, 2017). "62.7% (32 cases) of thyroid cancer samples with high Trop2 expression (51 cases) exhibited high levels of MMP2, whereas 64.4% (29 cases) of samples with low Trop2 expression (45 cases) showed low levels of MMP2 (p < 0.05) (Spearman rho = 0.276, P = 0.007)." (PMID 28709407, 2017). "In addition, we have recently shown that estrogen enhances thyroid cancer cell proliferation and metastasis associated events such as migration, adhesion and invasion, at least partly by induction and activation of essential proteolytic enzymes, mainly matrix metalloproteinases-2 (MMP-2) and MMP-9." (PMID 22548798, 2012). "However, the correlation between MEG3 expression and MMP-2 production in CAFs requires necessary further investigation and validation in thyroid cancers." (PMID 36077709, 2022). "Deletion of RET in thyroid carcinomas has been shown to reduce the production of MMP2 and MMP9." (PMID 33020210, 2020). "Previous studies have indicated that MMP2 and -9 enhance invasion of thyroid cancer cells." (PMID 29734379, 2018). "Moreover, zymography were performed to test the MMP2 enzymatic activity in Trop2 dysregulated thyroid cancer cells." (PMID 28709407, 2017).
thyroid cancer (continued). "Additionally, considering the importance of MMPs in tumor metastasis, we also investigated the impact of N-cadherin on the transcription of MMP-2,-9, and -14 in thyroid cancer cells." (PMID 28042956, 2017). "Moreover, we demonstrated that ectopic expression of PAX3 in thyroid cancer cells strongly inhibited the expression of MMP-2, -9 and -14, suggesting that PAX3-induced metastasis suppression is also related with the activity of MMPs." (PMID 27458157, 2016). "In addition, considering that matrix metalloproteinases (MMPs) play a critical role in tumor metastasis, we investigated the effect of SFN on expression of MMP-2 and -9 in thyroid cancer cells." (PMID 26312762, 2015). "Furthermore, a significantly higher prevalence of the active form of MMP-2 was observed in the supernatant obtained from fibroblast-thyroid cancer cell co-cultures compared with the levels of MMP-2 detected in the supernatant from fibroblast-non tumor thyroid cell co-cultures." (PMID 36077709, 2022). "MMP2 and MMP9 are gelatinases which use collagen IV as their main substrate and regulate thyroid cancer cell invasion." (PMID 29734379, 2018). "Recently, we have shown that blocking MMP2 and MMP9 attenuated S1P-evoked follicular ML-1 thyroid cancer cell invasion." (PMID 29734379, 2018). "Recently, we have reported that S1P induces secretion and activity of MMP2 and MMP9 through S1PR1,3, and that these MMPs are important for the S1P-evoked invasion of thyroid cancer ML-1 cells." (PMID 29734379, 2018). "Previous studies show that increased expression and activity of MMP2 and MMP9 in thyroid cancer cells promotes invasion." (PMID 29734379, 2018). "In the present study, we have investigated the expression, secretion and activity of MMP2 and MMP9 in thyroid cancer C643 cells where S1P inhibits invasion." (PMID 29734379, 2018). "In particular, previous studies have reported an increase in MMP-2 and MMP-9’s mRNA and protein levels in a variety of thyroid cancer cells." (PMID 30509240, 2018). "Among the MMP family members, an increased expression and activity of both MMP2 and MMP9, which use type IV collagen as their substrate, has been reported to correlate with enhanced invasion of thyroid cancer cells." (PMID 29137300, 2017). "The expression of uPA, MMP2, and MMP9 was negative in almost all NT and AG, while the ratios of positive uPA, MMP2, and MMP9 expression were high in thyroid cancer specimens." (PMID 29137300, 2017). "In the present study, the results demonstrated that overexpression of LKB1 could inhibit migration and invasion of thyroid cancer TPC-1 and BCPAP cells, and downregulate the expressions of MMP2 and MMP9." (PMID 35912012, 2022). "The CXCL12/CXCR4/CXCR7 axis may contribute to thyroid cancer development by regulating cancer cell migration and invasion via AKT, ERK signaling and MMP-2 activation." (PMID 28272462, 2017). "In addition, LKB1 overexpression could inhibit migration and invasion, downregulate MMP2 and MMP9 expressions, and reverse EMT in thyroid cancer cells." (PMID 35912012, 2022). "However, the role of MMP2 and MMP9 in S1P-evoked inhibition of invasion of thyroid cancer cells remained unknown." (PMID 29734379, 2018).
emphysema (32 papers, 2004 to 2025). "An increased MMP-2 expression in the lung periphery has been reported to be associated with worsened lung function and increased emphysema, thus it is important for lung tissue remodelling and inflammation in COPD." (PMID 33198714, 2020). "Interestingly, SP-D deficient mice have an emphysema phenotype and macrophages from SP-D deficient mice produce more MMP-2, -9, and -1235." (PMID 35031603, 2022). "In the same way, the inability of betamethasone to rebalance MMP-2-9/TIMP-1-2 ratio has been related to its inability to prevent the development of pulmonary emphysema associated to cadmium inhalation for 5 weeks and a similar mechanism has been described in dogs." (PMID 25313925, 2014). "Similar conclusions were reported previously indicating that the mechanisms of emphysema include activation of macrophages by LPS release and elastolytic enzymes (proteinase), mainly MMP-2, MMP-9, MMP-12, and cytokines from chemotactic neutrophils." (PMID 34136063, 2021). "These analyses demonstrated that circulating MMP2 was significantly higher among patients with clinically significant radiographic emphysema." (PMID 32171287, 2020). "There was also a significant association between OPN and sputum neutrophils, IL-8, matrix metalloproteinase-2 (MMP-2), and emphysema severity." (PMID 31664154, 2019). "In the present study of Myh10 deficiency during lung development and homeostasis, excess MMP2 activity and consequent defective ECM remodeling partially recapitulate the pathophysiological features of human COPD, especially emphysema." (PMID 30389913, 2018). "One recent study has shown the role of MMP9 and MMP2 in emphysema secondary to wood smoke (WS) exposure in a guinea pig model." (PMID 24802298, 2014). "Destruction of lung parenchyma in emphysema is thought to occur through excessive proteolysis mediated by the elastin-degrading enzymes MMP2, MMP9, and MMP12 from the MMP family, and by neutrophil elastase from the serine proteinase family." (PMID 15526056, 2004). "This is in agreement with our previous long-term study, which showed that BCX was able to decrease NNK/nicotine-induced emphysema in AJ mice and inhibit the expression of MMP-2 in vitro, and retinoic acid’s inability to protect against emphysema development in mice." (PMID 36771049, 2023). "Additionally, cadmium has a direct impact on the adherence junction proteins, causing the synthesis of pulmonary MMP-2 and MMP-9, and accelerating collagen and elastin breakdown that results in emphysema." (PMID 37749472, 2023). "MMP-2 and MMP-9 have already been implicated in the pathogenesis of emphysema, so they may be potential therapeutic targets in the emphysema phenotype of COPD." (PMID 33535173, 2021). "The present results are in accordance with those conclusions, which the upregulation of MMP9 and MMP2 could lead to pulmonary emphysema in rats exposed to WS." (PMID 24802298, 2014). "MMP-2 also may affect the induction of emphysema and alveolar wall damage." (PMID 28704475, 2017). "Others have shown that treatment with olaparib (PARP1 inhibitor) ameliorated MMP2 and MMP9 expression in an elastase-induced mouse model of emphysema." (PMID 33172999, 2020). "VDR-deficient mice exhibit increased inflammation in the lungs with up-regulation of matrix metalloproteinase-2 (MMP-2), MMP-9, and MMP-12, the development of emphysema and a decline in lung function mimicking COPD in humans." (PMID 33042125, 2020). "In the early onset of emphysema/COPD mice had increased influx of inflammatory cells and upregulation of MMPs, such as MMP-2, MMP-9, and MMP-12 in the lung." (PMID 30402133, 2018). "In the present study, exogenous administration of Gal-9 in an emphysema animal model reduced the levels of MMP-9, MMP-2 and TIMP-1 in BALF, and these MMPs levels correlated significantly with the number of neutrophils in BALF." (PMID 28704475, 2017). "Gal-9 significantly reduced MMP-9, MMP-2 and TIMP-1 levels in BALF on day 7 in the emphysema model." (PMID 28704475, 2017).